LOLI1 (lncRNA oncogene in liver cancer 1)
Gene: Long non-coding RNA gene on chromosome 3 (113,040,505 to 113,104,434, reverse strand). Ensembl gene ENSG00000241219.
Diseases named in the same sentence as LOLI1 in open-access papers:
LOLI1 is named in the same sentence as 5 diseases in open-access papers, as found by Europe PMC text mining. Sharing a sentence is not in itself a finding about the gene and the disease. The quoted sentences say what the papers report.
head and neck cancer (1 paper, 2023). A primary or metastatic malignant neoplasm affecting the head and neck. "The ability of ExInAtor2 to identify cancer lncRNAs was demonstrated by extensive functional studies, including for two lncRNAs, LOHAN1 (head and neck cancer) and LOLI1 (hepatocellular carcinoma)." (PMID 37291246, 2023).
hepatocellular carcinoma (1 paper, 2023). A malignant tumor that arises from hepatocytes. "ENSG00000241219 (RP11-572M11.1), herein named LOLI1 (LncRNA Oncogene in Liver cancer 1) displayed elevated mutation rates in Hepatocellular Carcinoma (HCC) tumours and was detected as driver in both the PCAWG and HFM datasets." (PMID 37291246, 2023).
tumours (1 paper, 2023). "Having established that LOLI1 promotes cell growth in a number of backgrounds, we next asked whether tumour mutations can enhance this activity, as would be expected for driver mutations." (PMID 37291246, 2023).
LOLI1 also shares sentences with these, for which no sentence is quoted: cancer (1 paper); liver cancer (1).